CSF2 (colony stimulating factor 2)
Diseases named in the same sentence as CSF2 in open-access papers (continued):
Sharing a sentence is not in itself a finding about the gene and the disease.
cancer (continued). "Based on previous reports suggesting that CSF2 could inhibit the development of cancer, we further investigated the serum samples from patients with EC, CRC, GC, LC, and MC." (PMID 36844744, 2023). "In addition to its immunomodulatory functions, emerging evidence suggests that CSF2 also contributes to cancer cell migration and invasion in the context of cancer metastasis, and indeed we detected highly increased expression of CSF2." (PMID 38003292, 2023). "The colony-stimulating factors increase the number of neutrophils and induce their activation, NETs can be released by the systemic release of colony-stimulating factors in cancers, which might be one of carcinogenic effects of CSF2." (PMID 35252353, 2022). "Administration of curcumin to cancer patients resulted in a decrease in CSF2." (PMID 35405942, 2022). "Moreover, CSF2 is used to augment the recruitment and maturation of DCs in clinical trials for cancer therapy." (PMID 34248982, 2021). "Importantly, HB-EGF treatment in cancer cells and CAFs mono-cultures shows that: LIF is strongly upregulated only by CAFs, indicating that these are the cells responsible for its production when in co-culture; CSF2 was upregulated by HB-EGF treatment both in cancer cells and in CAFs." (PMID 39262776, 2024). "These known NF-κB target genes, such as IL6, IL8, BIRC2 (clAP-1), ICAM1, YAP1, CDKN1A (p21), CSF2, CCDN1, IL1A, IL1B, and so on, include many that have been independently confirmed to be differentially expressed and pathologically implicated in HNSCC and other cancers." (PMID 18334025, 2008). "Bioinformatics analysis identified critical candidate genes (Col4a6, Csf2) and pathways (PI3K-Akt, TNF) in inflammation-to-cancer conversion." (PMID 41415031, 2025). "Cancer cells express various cytokines, chemokines, and growth factors such as IL-6, CCL2, CXCL8, CSF1, and CSF2, which impact vascular permeability, lymph angiogenesis, and metastasis." (PMID 37894465, 2023). "In the present study, we investigated the relationship between CSF2 and atherosclerosis-related diseases, including AIS, AMI, DM, CKD, and cancer based on data from previous studies." (PMID 36844744, 2023). "In this study, we examined the serum anti-CSF2 antibody levels in patients with AIS, AMI, DM, CKD, and cancer." (PMID 36844744, 2023). "The activation of genes such as NR4A3, MET, ZEB1, CSF1, CSF2, CSF3, which can be involved in transcriptional dysregulation in cancer or hematopoietic cell lineage signaling pathways, can also be involved in cell differentiation." (PMID 37606991, 2023). "A-ME/CFS subjects who developed malignancies (n=8) had higher levels of IL5, CSF2 and PDGFBB than other A-ME/CFS subjects." (PMID 28375204, 2017). "Many E2 regulated genes in other normal and cancer cell types were also regulated in MOE cells including Pgr, Greb1, Csf2, and Dhrs9, while other E2 regulated genes in MCF7 cells were not regulated (Nrip1) or even expressed (Tff1) in MOE cells." (PMID 26879975, 2016). "Our gene expression analysis also revealed up-regulation of CSF-2 (GM-CSF) in macrophages grown as co-culture with cancer cells and CSF-2, CSF-3 and CSF1R up-regulation in cancer cells grown together with macrophages." (PMID 22353646, 2012). "Granulocyte-macrophage colony-stimulating factor (GM-CSF, also known as colony stimulating factor 2, CSF2) is a cytokine that stimulates the production of various myeloid cell subsets in response to stress, infections, and cancers." (PMID 40055311, 2025). "Furthermore, monocyte dynamics are reprogrammed in cancer patients through alterations in systemic cytokines, such as colony-stimulating factor 1 (CSF1), CSF2 and CSF3." (PMID 41444555, 2025). "Moreover, by reducing HB-EGF expression in cancer cells and then co-culturing the cells with CAFs, we also observed strong downregulation of both LIF and CSF2 expression." (PMID 39262776, 2024).
cancer (continued). "MDSCs expand peripherally in both cancer patients and tumor-bearing mice, at least in part driven by the systemic effects of cancer cell-derived cytokines that influence hematopoiesis in the bone marrow, including IL6 and CSF2." (PMID 36319998, 2022). "Other cancer progression-related genes that became differently expressed in PNX0010 cells under PARG overexpression are serpin family E member 1 (SERPINE1), colony-stimulating factor 2 (CSF2 or GM-CSF), ubiquitin specific peptidase 10 (USP10), and growth differentiation factor 15 (GDF15)." (PMID 34638458, 2021). "The classical activation pathway, in the presence of Th1-derived cytokines such as IFN-γ, colony stimulating factor 2 (CSF2), or toll-like receptor (TLR) activation, gives rise to the M1-like macrophage phenotype considered more protective against cancer cells." (PMID 34204306, 2021). "The mRNA expression of cytokines involved in neutrophil recruitment to cancer sites, such as colony‐stimulating factor‐2 (CSF‐2), CSF‐3 and chemokine (C‐X‐C motif) ligand 1 (CXCL1), was determined, and CSF‐2 and CSF‐3 were reduced and CXCL1 expression was increased in CT26‐mP2X7R cells." (PMID 32735377, 2020). "We found that already at these early stages of progression, HER2+ cancer cells upregulated expression of Ccl2 but not Csf2, Csf1, Il1β, and Il6." (PMID 29295986, 2018). "Jun, CSF2 and IL-8 showed increased expression in IMR90 cells, whereas, NFκB1, NFκBIA, FN1 (fibronectin 1), GADD45A, BIRC2, TMEPAI (prostate androgen induced RNA) and CEBPB (CCAAT/enhancer binding protein) were up regulated in cancer cells." (PMID 22321936, 2012). "Colony-stimulating factor 2 (CSF2) is involved in many cancers, but not BCa." (PMID 38817867, 2024). "CSF2 activates AKT1-, ERK1/2-, mTOR- but not JAK/STAT-dependent signaling cascades, which are active in many cancer stem cells." (PMID 28031533, 2017).
infection (761 papers, 1990 to 2026). The state of being infected such as from the introduction of a foreign agent such as serum, vaccine, antigenic substance or organism. "Experiments with CSF2−/− and wild-type mice showed that deficiency of CSF2 induced a delay in the onset of inflammatory-mediated tissue damage in the spleens and livers after the infection with Salmonella Typhimurium." (PMID 40141330, 2025). "Additional cytokine/chemokine transcripts induced by invasive infection were e.g., Ccl3, Ccl4, Ccl7, Cxcl10, and Csf2 (encoding GM-CSF)." (PMID 38291037, 2024). "Mice with a B cell restricted deficiency to produce GM-CSF (Csf2-/-/μMT) showed reduced cell numbers in tracheobronchial lymph node 4 days post-infection compared to WT/μMT control mice." (PMID 35493510, 2022). "Regardless, morbidity and disease severity remained almost completely unaffected in Batf3-deficient compared to wild-type mice, while Csf2−/− mice succumbed to infection." (PMID 24699679, 2014). "To further rule out that a defect in CD103+ DCs contributed to the susceptibility of Csf2−/− mice to influenza virus infection, we selectively depleted AM in wild-type mice prior to infection using clodronate liposomes." (PMID 24699679, 2014). "The CSF2 gene encoding the cytokine GM-CSF is the most overexpressed, and we report for the first time that CSF2 expression is contact and conidial-viability-dependent during infection." (PMID 36354918, 2022). "In addition, CCR5-deficiency during infection affected the upregulation of cytokine genes such as Csf2, Csf3, Cxcl1, Edn1, and Il6 and other genes associated with immune response (i.e., Gimap6, Mcoln2) and migration (i.e., Cyfip2)." (PMID 31506064, 2019). "Csf2, which encodes a cytokine involved in granulocyte production, and the gene encoding Ficolin B, a pattern recognition receptor, both demonstrate significant transcript increases only at Day 1 at the site of infection." (PMID 25901897, 2015). "Recombinant GM-CSF (rGM-CSF) controls M. tuberculosis growth in mouse peritoneal macrophages and human monocytes, and GM-CSF-deficient (Csf2-/-) mice have significantly higher bacterial burden in the lungs compared to wild-type and succumb more rapidly to infection." (PMID 35877763, 2022). "In addition, the induction of systemic responses via the acute-phase response and increasing serum concentrations of CSF3 and CSF2 is linked to an increase in neutrophil and macrophage numbers at the site of infection in mice, and is regulated by IL-17 amongst other cytokines." (PMID 31998322, 2019). "In this study, we investigated the potential role of GM-CSF (or CSF2) in the host response to C. gattii using a murine model of infection." (PMID 41945616, 2026). "The results showed that both WT and Csf2 KO mice reached peak footpad swelling during the early phase of infection (weeks 1-2), followed by a gradual decline, indicating a progression from mild to severe inflammation and subsequent resolution." (PMID 41190069, 2025). "In both WT and Csf2 KO mice, footpad tissues exhibited significant swelling and ulceration within 1–2 weeks post-infection." (PMID 41190069, 2025). "Histopathological examination of footpad tissues showed PAS-positive fungal hyphae in both WT and Csf2 KO mice at 1 week post-infection." (PMID 41190069, 2025). "Footpad swelling measurements indicated that both WT and Csf2 KO mice reached peak swelling levels during the early stage of infection (weeks 1-2), followed by a gradual decline." (PMID 41190069, 2025). "The RNASeq analyses of MDMs were validated using quantitative RTPCR based on CCL19, highly induced in the presence of hSAA-1, CSF-2, induced after infection with tubercle bacilli, and CXCL8, induced in the presence of either stimuli." (PMID 37781389, 2023). "P. micra infection was found to up-regulate the expression of IL-5 (P=0.0001), IL-8 (P=0.0001), CCL20 (P=0.0001), and CSF2 (P=0.0001) at 2 hr post-infection." (PMID 37218575, 2023).
infection (continued). "Quantification of the expression of six inflammatory markers (IL-5, IL-8, IL-22, CCL20, TIMP1, CSF2) was carried out at 2, 24, and 48 hr post-infection." (PMID 37218575, 2023). "Il17 and Il22 transcripts were reduced in Rorc−/− bladders following infection compared with controls, with similar levels of Csf2." (PMID 35845169, 2022). "Studies have shown that epithelial cells infected by Chlamydia trachomatis can release CSF2, which can mediate the influx and activation of inflammatory cells at the infection site." (PMID 33875006, 2021). "The gene csf2 was significantly upregulated after infection with the NmB wild type strain as well as during the infection with the NmB capsule-deficient mutant when Erk1/2 signalling was inhibited." (PMID 34863201, 2021). "Basal levels of Csf2 are low under homeostatic conditions but can be quickly elevated during infection or inflammation." (PMID 32733471, 2020). "Csf2 was reported to facilitate the development of the immune system and promote defense against infections." (PMID 32733471, 2020). "Instead the highest diversity in CSF1 and CSF2 was due to mixed infection with 2 or more different VZV clades." (PMID 29986093, 2018). "In contrast, the initial HAM response to infection displays a lag phase with few genes significantly up-regulated at the 2 h post-infection time point (CSF2, IL-1B, IL-6, IL-10, IL-21)." (PMID 29847580, 2018). "The protective response to infection in B2−/− mice also was also associated with temporal deployment of CEBP transcription factors, continued expression of Csf2, and replenishment and differentiation of alveolar macrophages (AMs)." (PMID 28779131, 2017). "After infection, particularly at the 6 h and 8 h time points, CSF2, CCL2, MMP1, and MMP10 proteins were expressed at higher levels in CF than CTRL cells, although the differences were not statistically significant." (PMID 26485688, 2015). "Strikingly, whereas all WT mice recovered from infection, moribund Csf2−/− mice had to be euthanized between day 10 and 12 post-infection." (PMID 24699679, 2014). "Accordingly, respiratory function as measured by arterial oxygen levels was critically impaired at the time when Csf2−/− mice succumb to infection." (PMID 24699679, 2014). "We therefore assessed the secretion of three key cytokines, IL-6, IL-8 and GM-CSF (also called CSF-2) from the prostate-derived epithelial cell-line RWPE-1 in response to infection with P. acnes." (PMID 20420679, 2010). "Expression of the chemokines genes (Ccl-2, >200-fold; csf2, >10-fold and Ccxl-10, ∼30-fold) and surface receptor molecules (FasL, >2.5 fold and IL-2R, 4-fold) were upregulated at the initial phase of infection, but decreased at later time points." (PMID 20062542, 2010). "In response to P. aeruginosa, genes associated with IFN-γ response to infection (CXCL10, IL-24, IFNγR2) and other mediators of anti-infectious responses (CSF2, MMP1, MMP3, TLR2, S100 calcium-binding proteins A) were markedly up-regulated in wild-type TG cells." (PMID 19399182, 2009). "Numerous studies have reported the upregulation of proinflammatory cytokines and chemokines in the mouse brain following infection, with notable examples of cytokines including IFNα/β, IFNγ, TNFα, GM-CSF (CSF2), LIF, and Interleukins-1; −4; −6; −12b; −17; and −23." (PMID 41442410, 2026). "The lack of more profound differences in gene expression and the decrease of Csf2 transcription upon infection was surprising and may reflect the overall exhaustion of the infected BM." (PMID 37383236, 2023). "Interestingly, Csf2-/-/μMT mice had reduced numbers of CD103+ dendritic cells in tracheobronchial lymph node 4 days post-infection suggesting a reduced T cell activation." (PMID 35493510, 2022).
infection (continued). "The Il2 and Csf2 genes were not only the first and third most important genes for the classification of samples regarding the presence of a previous infection but they were also among the genes with the highest correlation with the concentration of different cytokines, together with the Il2ra gene." (PMID 35795182, 2022). "Knockdown of Prdm1 in IEC4.1 cells resulted in enhanced antimicrobial activity against C. parvum infection induced by IFN-γ, with a significant further decrease in the infection burden and a further increase in the expression of defense genes, including Nos2, Ido1, and Csf2." (PMID 34488445, 2021). "CSF2 is well known for its ability to counter myelosuppression and is administered after radiological events to boost and activate the immune response to infection." (PMID 29351567, 2018). "To assess whether the AM play an important role in resistance to other pulmonary viral infections, we assessed the outcome of infection with vaccinia virus (WR) in Csf2−/− and control WT mice." (PMID 24699679, 2014). "Of these, a lncRNA, named NR_045064, could reduce infection burden of parasites in murine intestinal epithelial cells in vitro and in the enteroids of neonatal mice by promoting expression of host defense genes (e.g. Csf2, Nos2, and Cxcl2)." (PMID 35999576, 2022). "Remarkably, CSF2 (encoding granulocyte-macrophage colony-stimulating factor), IL-6 (interleukin-6), IL-12B (interleukin-12 subunit beta), CSF3 (granulocyte colony-stimulating factor), and TNF (tumor necrosis factor) were extremely highly expressed upon infection with WT V. vulnificus (log2 FC > 8)." (PMID 32817457, 2020). "To investigate whether the increased nucleotide diversities of samples CSF1, CSF2, and PLAS2 were due to mixed infections, we substituted variant alleles within distinct frequency ranges into the consensus sequences for the same samples and generated additional network phylogenies." (PMID 29986093, 2018). "Importantly, the fatal outcome of infection resulted from the absence of GM-CSF production by non-hematopoietic cells as demonstrated by a higher susceptibility of WT→Csf2−/− compared to Csf2−/−→WT BM chimeras." (PMID 24699679, 2014). "Similarly, CSF2 release by Ct infected epithelial cells may mediate the influx and activation of inflammatory cells at the site of infection." (PMID 20015396, 2009). "Conversely, infection significantly reduced levels of IL-1α, IL-2, IL-9, IL-10, IL-12 (p70), IL-13, IFNγ, IL-3, CCL4 (MIP-1β), CSF 2 (GM-CSF), CCL5 (RANTES), and TNFα." (PMID 37790429, 2023). "Infection with SARS-CoV-2 and several influenza viruses can lead to alterations in CSF2 and IL-11 expressions." (PMID 36093436, 2022). "After 48 h of infection, the levels of TNF, CXCL8, IL6, CSF2, CD180, CD14, and CCL2 levels increased and those of IL-10, INFB1, and CXCL10 decreased." (PMID 36296238, 2022). "Additionally, our pathway analysis revealed seven genes, IL-4, IFNγ, TLR4, CXCL8, IL-18, CSF2 and TNFα, are involved in the morphological and behavioral changes of macrophages, monocytes, granulocytes, and dendritic cells (DCs) and their recruitment into infection sites." (PMID 34753991, 2021). "Other immune regulatory molecules, such as CD14 and CSF2, were significantly up‐regulated, while others, such as TLR4, IRF9 and CD36, were significantly down‐regulated after infection with H37Rv." (PMID 34632719, 2021). "CSF2 and CSF3 respond to infection by inducing inflammation and recruiting lymphocytes to the site of infection." (PMID 34358063, 2021). "Among hub genes, most were affected by infection of human or avian influenza viruses such as H7N7, H1N1, H7N9, H3N2, and H5N1; CSF2 and S100A9 were exclusive to SARS-CoV-2 infection." (PMID 34376762, 2021). "During infection, CSF3 works along with IL3, IL6, and CSF2 to stimulate neutrophil granulopoiesis in the bone marrow to restore neutrophil homeostasis." (PMID 33362771, 2020).